KDM2A (lysine demethylase 2A)
Diseases named in the same sentence as KDM2A in open-access papers (continued):
Sharing a sentence is not in itself a finding about the gene and the disease.
breast carcinoma (continued). "Breast cancer cell line MCF-7 cells were treated with metformin to examine whether metformin activated KDM2A to reduce rRNA transcription." (PMID 31822720, 2019). "We previously demonstrated that KDM2A is expressed in breast cancer tissues." (PMID 31413816, 2019). "However, in support of our findings, depletion of KDM2A has been shown to increase the sensitivity of breast cancer cells to cisplatin-induced DNA damage." (PMID 29662616, 2018). "KDM2A exhibits proliferative properties and is upregulated in lung, gastric and breast cancer." (PMID 30059280, 2018). "Our results showed that the reduction of SOX2 in KDM2A-depleted breast cancer cells could be fully rescued by ectopic expression of JAG1 suggesting the involvement of NOTCH signaling in the regulation of SOX2 transcription." (PMID 27029061, 2016). "In addition, we tried to elucidate how KDM2A regulates the behaviors of breast cancer cells and identified JAG1 as a key downstream effector for KDM2A to promote stemness and angiogenesis in breast cancer." (PMID 27029061, 2016). "We next investigated the expression of KDM2A in breast cancer cell lines." (PMID 27029061, 2016). "Similarly, the PROGgeneV2 database indicated a poor overall survival of breast cancer patients with high KDM2A expression (p=0.0425)." (PMID 27029061, 2016). "Results of this study suggest KDM2A is a potential therapeutic target for breast cancer." (PMID 27029061, 2016). "Knockdown of KDM2A in breast cancer abolished these stimulatory effects which could be reversed by JAG1 overexpression indicating JAG1 is involved in KDM2A-induced tumor angiogenesis." (PMID 27029061, 2016). "Our results demonstrate that KDM2A associated with Rb and E2F1 in a cell cycle dependent manner in breast cancer cells indicating that this interaction could probably be regulating cell cycle progression." (PMID 25029110, 2014). "Taken together, these results indicate that the E2F1-mediated expression of MMP2, MMP9, MMP14, and MMP15 might be repressed by KDM2A, eventually hindering the migration and invasion of breast cancer cells." (PMID 25029110, 2014). "Since certain histone demethylases are known to bind to Rb and regulate E2F function we examined whether KDM2A has similar functions, especially in breast cancer cells." (PMID 25029110, 2014). "The expression of KDM2A in the MEPCs also suggested a tumor suppressor function for KDM2A, consistent with the myoepithelial cell function in the breast; supporting this contention, KDM2A repressed migration and invasion of breast cancer cells." (PMID 25029110, 2014). "We first analyzed KDM2A expression in breast cancer tissue microarray (TMA)." (PMID 25029110, 2014). "Since KDM2A could bind to E2F1, transient transfection experiments were conducted in MCF7 breast cancer cells to assess whether KDM2A had an effect on the transcriptional activity of E2F1." (PMID 25029110, 2014). "The differential expression of KDM2A raises the possibility that it might serve as a good marker for myoepithelial cells and therefore act as a biomarker for breast cancer progression from non-invasive to more invasive phenotype." (PMID 25029110, 2014). "However, the detailed molecular mechanism by which IL-6 regulates KDM2A in breast cancer remains unclear." (PMID 37821959, 2023). "However, the molecular mechanism by which breast cancer-secreted IL-6 regulates the expression of KDM2A remains unclear." (PMID 37821959, 2023). "However, some studies have indicated a tumor suppressor effect of KDM2A in breast cancer." (PMID 36291773, 2022). "We previously reported that lysine-demethylase 2A (KDM2A), a Jumonji-C histone demethylase, is activated by gallic acid to reduce H3K36me2 levels in the rRNA gene promoter and consequently inhibit rRNA transcription and cell proliferation in the breast cancer cell line MCF-7." (PMID 35053178, 2021). "It is possible that breast cancer cell-released factors may upregulate stromal KDM2A." (PMID 33024266, 2021).
breast carcinoma (continued). "We previously showed that a JmjC-type KDM, KDM2A, decreases the dimethylated lysine 36 of histone H3 (H3K36me2) but not trimethylated lysine 36 of H3 (H3K36me3) in the rRNA gene (rDNA) promoter, and represses rRNA transcription under starvation in breast cancer cells." (PMID 33050392, 2020). "Therefore, the effect of KDM2A depletion in breast cancer cells was further investigated." (PMID 27029061, 2016). "Studies have demonstrated that mild glucose starvation promotes KDM2A‐induced demethylation of H3K36me2, which decreases rRNA transcription and proliferation via the AMPK signaling pathway in breast cancer." (PMID 35697678, 2022). "It was found that HP1γ was expressed in all breast cancer tissues examined, including TNBC, as we have previously shown in KDM2A." (PMID 31413816, 2019). "Here, we demonstrate that knockdown of KDM2A significantly increases the 5′-hydroxymethylcytosine (5′-hmc) level in genomic DNA and expression of tet-eleven translocation 2 (TET2) in various breast cancer cell lines." (PMID 28785073, 2017). "KDM2A along with KDM5B, have the highest frequency of gene amplifications and over expressions in breast cancer with respect to JmjC enzymes." (PMID 28536364, 2017). "Results of our study support the notion that SOX2 is a master regulator in maintaining breast cancer stem cells and provide the first evidence that SOX2 is a downstream mediator of KDM2A to promote cancer stemness." (PMID 27029061, 2016). "Conversely, KDM2A was found to regulate E2F1-mediated gene transcription and thus to suppress the invasion and migration in breast cancer cells." (PMID 26430963, 2015). "Current data suggests that KDM2A works in conjunction with E2F1 to affect FLT-1 and KDR expression in endothelial cells and MMP expression in breast cancer cells." (PMID 25029110, 2014). "Experiments were conducted to investigate the role of KDM2A in the invasion of T47D and MCF7 breast cancer cells by Boyden chamber assay, using established protocols." (PMID 25029110, 2014). "Similarly, inhibition of the lysine demethylase 2A (KDM2A), which catalyzes the trimethylation of H3K36, sensitized breast cancer cells to cisplatin and blocked tumorsphere formation by inhibiting Notch." (PMID 34680255, 2021). "Co-culture with MDA-MB-231 breast cancer cells enhanced PD-L1 expression in the RMF-EG fibroblasts, which could be significantly reduced by treatment of daminozide or knockdown of KDM2A." (PMID 33024266, 2021). "We found that gallic acid reduced rRNA transcription and cell proliferation in a KDM2A-dependent manner in the breast cancer cell line MCF-7 but not in non-tumorigenic MCF10A cells." (PMID 33050392, 2020). "The results show that most of breast cancer cell lines express HP1γ and KDM2A mRNAs similarly to those of MCF-7 cells, and triple negative breast cancer cell lines, including MDA-MB-231, also express HP1γ and KDM2A." (PMID 31413816, 2019). "To rule out the cell line-specific effect, we inhibited KDM2A in SkBr3 breast cancer cells and found the expression of JAG1 and PDGFA was also reduced." (PMID 27029061, 2016). "We previously showed that a JmjC histone demethylase, lysine-demethylase 2 A (KDM2A), decreases the dimethylated lysine 36 of histone H3 (H3K36me2) in the ribosome RNA gene (rDNA) promoter and represses rRNA transcription under starvation in breast cancer cells." (PMID 31822720, 2019). "Interestingly the small isoform of KDM2A, which lacks the JmjC domain, is more highly expressed than the full isoform in a subset of breast cancer, suggesting an oncogenic role KDM2A independent of direct demethylase activity." (PMID 28536364, 2017). "Knockdown of KDM2A in breast cancer cells reduced proliferation but not viability." (PMID 27029061, 2016).
breast carcinoma (continued). "Similarly, the histone demethylase KDM2A (induced) acts as E3 ligase to regulate RNAPII ubiquitination and ER-mediated gene repression, whereas ATAD2 (repressed) regulates p300-mediated histone hyperacetylation to activate ER target genes involved breast cancer biology." (PMID 38625038, 2024). "This study revealed the non-canonical molecular mechanism of IL-6 secreted by breast cancer upregulated KDM2A expression in CAFs via a novel STAT3/NFκB p50 axis, which STAT3 complexed with NFκB p50 in NFκB p50 binding motif of KDM2A promoter." (PMID 37821959, 2023).
gastric cancer (14 papers, 2015 to 2024). A primary or metastatic malignant neoplasm involving the stomach. "For example, the dysregulation of enzymes like KMT2D (an HMT) and KDM2A (an HDM) is linked to various cancers including gastric cancer by influencing the chromatin structure and gene activity." (PMID 39765675, 2024). "KDM2A gene encodes a member of the F-box protein family, and its aberrant expression can be observed in a variety of cancers, such as gastric cancer." (PMID 37726685, 2023). "It has been described that KDM2A is frequently overexpressed in non‐small cell lung cancer tumors and gastric cancers and can promote the growth and motility of cancer cells." (PMID 34117688, 2022). "In gastric cancer, the upregulation of KDM2A by LINC00460, as a molecular sponge for miR-342-3p targeting KDM2A, promoted the proliferation, migration and invasion of gastric cancer cells." (PMID 34575926, 2021). "For example, it targets the promoter region of KDM2A, increasing its expression consequently inhibiting the proliferation and migration of gastric cancer cells." (PMID 34052838, 2021). "Furthermore, the introduction of miR-29b molecules into breast or stomach cancer cells reduced tumor growth in vitro and in vivo (in a mouse model), by influencing the Akt3 and KDM2A pathways." (PMID 35269947, 2022). "Similarly, gastric cancer tissues have been found to have an increased level of KDM2A expression and forced expression of KDM2A promoted cell growth and migration." (PMID 34391411, 2021). "KDM2A expression was found to be increased in gastric cancer tissues, and KDM2A may regulate the growth and motility of gastric cancer cells by down-regulating the expression of tumor suppressor programmed cell death 4 (PDCD4) in the progression of gastric cancer." (PMID 26430963, 2015). "Lysine demethylase 2 A (KDM2A), also known as FBXL11 and JHDM1A, is highly expressed in ovarian, pancreatic, colorectal, breast, and gastric cancer." (PMID 35697678, 2022). "Lysine demethylase 2A (KDM2A) is highly expressed in CAFs and is involved in the carcinogenesis of breast, ovarian, lung, and gastric cancers." (PMID 36291773, 2022). "Finally, miR-625-5p/NFIX, miR-124-3p/EZH2, miR-625-5p/STAT3 and miR-29b/KDM2A are other molecular axes regulated by LINC00511 in gastric cancer." (PMID 37124625, 2023).
lung cancer (14 papers, 2014 to 2023). A malignant neoplasm involving the lung. "Overexpression of KDM2A in lung cancer was associated with poor prognosis and is believed to promote lung tumorigenesis by repressing DUSP3 (dual-specificity phosphatase 3) and activating ERK1/2." (PMID 25029110, 2014). "We identified and validated a set of novel druggable non-oncogene vulnerabilities preferentially related to different lung cancer histotypes; dependency on KDM2A is associated with AD and SCLC, dependency on CSNK1A1 is associated with AD, and dependency on LTB4R2 is associated with SCC." (PMID 34298691, 2021). "KDM2A overexpression also increases lung cancer growth by means of epigenetically increasing ERK1/2 and JNK1/2 signaling." (PMID 37218871, 2023). "Inherently, KDM2A is known to function as an oncogene in lung cancer via activation of the ERK pathway." (PMID 35508523, 2022). "KDM2A has been demonstrated to promote tumorigenesis in different cancer settings, including lung cancer." (PMID 34298691, 2021). "KDM2A overexpression was found to increase cell proliferation and invasion through activation of ERK1/2 signaling in lung cancer as well as being associated with poor prognosis in lung cancer patients." (PMID 34220955, 2021). "A study on NSCLC tumor and the lung cancer cell line found that histone H3 lysine 36 (H3K36) demethylase KDM2A (FBXL11 and JHDM1A) activates ERK1/2 by the epigenetic regulation of DUSP3." (PMID 33670008, 2021). "In lung cancer, KDM2A was reported to be a novel oncogenic promoter of non-small cell lung cancer (NSCLC), and the overexpression of KDM2A was shown to promote tumorigenicity and metastasis by epigenetically enhancing ERK1/2 signaling in NSCLC." (PMID 26430963, 2015). "KDM2A/JHDM1A/FBXL11 acts on histone mono- and dimethylated histone H3K36 and is implicated in lung cancer and the epigenetic silencing of chromatin." (PMID 26461474, 2015). "Recent discovery of highly selective inhibitor of KDM2A might provide opportunities to develop KDM2A targeted therapy for lung cancer." (PMID 30002791, 2018). "KDM2A was identified as one of the most upregulated histone demethylases in lung cancer." (PMID 27029061, 2016). "The potential role of KDM2A in carcinogenesis has been demonstrated recently in lung cancer." (PMID 27029061, 2016). "Results of the study suggested KDM2A is an oncogene in lung cancer." (PMID 27029061, 2016). "KDM2A may reactivate the expression of COX-2 gene by decreasing H3K36me2 near the COX-2 promoter in human lung cancer cells." (PMID 26430963, 2015). "In lung cancer, the dual-specificity protein phosphatase 3 (DUSP3) expression is suppressed by KDM2A-dependent H3K36 demethylation at its promoter, which raises ERK1/2 and JNK1/2 functions." (PMID 37218871, 2023). "Overall, in our study we described the use of an innovative integrative genomic approach to identify new candidate genes for lung cancer treatment, namely CSNK1A1, KDM2A, and LTB4R2." (PMID 34298691, 2021). "Through this analysis, we identified CSNK1A1, KDM2A, and LTB4R2 as relevant druggable essentiality genes in lung cancer." (PMID 34298691, 2021). "In addition, this strategy allowed us to identify three target genes that are poorly characterized and still require biological validation in lung cancer: CSNK1A1, KDM2A, and LTB4R2." (PMID 34298691, 2021). "We reasoned that CSNK1A1, KDM2A, and LTB4R2 dependencies could become therapeutic intervention points in lung cancer, so we proceeded with further characterization." (PMID 34298691, 2021). "KDM2A, but not its homologue KDM2B, was reported to be associated with lung cancer." (PMID 30002791, 2018).
prostate carcinoma (11 papers, 2014 to 2023). A carcinoma that arises from epithelial cells of the prostate gland. "The tumor-suppressing, heterochromatin-associating lysine demethylase 2A (KDM2A) is downregulated in prostate cancer." (PMID 30627137, 2018). "Therefore, as a result of KDM2A deficiency, increased levels of pericentromeric alpha satellite DNA is observed in prostate cancer, particularly in the metastatic stage." (PMID 37958565, 2023). "It is also known that the lysine-specific demethylase 2A (KDM2A), which is specific for H3K36, is downregulated in prostate cancer and the KDM2A level is negatively correlated with pericentromeric heterochromatin transcription." (PMID 35885937, 2022). "The lower the level of KDM2A expression, the higher pericentromeric heterochromatin transcription and the more severe the tumour grade in prostate cancer." (PMID 35205427, 2022). "Using a proliferative recovery assay, the knockdown of KDM2A significantly inhibited recovery arrest of prostate cancer cells in androgen depleted conditions." (PMID 27792127, 2016). "For instance, the lysine-specific demethylase 2A (KDM2A) is a tumor suppressor gene, which is downregulated in prostate cancer." (PMID 25788984, 2015). "Study on human prostate cancers showed low levels of KDM2A in prostate cancers while a recent study states that high levels of KDM2A correlates with poor prognosis in NSCLC patients." (PMID 25029110, 2014). "However, the KDM2A properties are likely to be context dependent since in prostate cancer KDM2A is downregulated, and under stress conditions it exhibits anti-proliferative properties by repressing ribosomal RNA (rRNA) genes." (PMID 30059280, 2018). "Similarly, downregulation of Lysine-specific demethylase 2A (KDM2A) in prostate cancer leads to aberrations in compaction status and activation of pericentromeric repeats." (PMID 28698521, 2017). "It is also known that the lysine-specific demethylase 2A (KDM2A), which is specific to H3K36, is downregulated in prostate cancer, and the KDM2A level is negatively correlated with pericentromeric heterochromatin transcription." (PMID 37958565, 2023). "For instance, the lysine-specific demethylase 2A (KDM2A)—which is specific for H3K36—is a tumour suppressor and is downregulated in prostate cancer." (PMID 35205427, 2022). "Silencing of KDM2A, FAM83H and GLYATL1 significantly inhibited the clonogenicity of prostate cancer cells in vitro." (PMID 27792127, 2016).
Obesity (6 papers, 2012 to 2025). Accumulation of substantial excess body fat. "Given its extensive biological significance, KDM2A has been implicated in inflammatory-driven diseases, including cancer and obesity." (PMID 37892137, 2023). "In the current study, we generated a macrophage-specific Kdm2a-deficient mouse model to dissect the impact of epigenetic regulation by Kdm2a on the development of obesity." (PMID 33462408, 2021). "Given that loss of Kdm2a orchestrated alternative activation of macrophages, we thus used KO mice to dissect the impact of histone methylation on the pathoetiology of obesity." (PMID 33462408, 2021). "Our results demonstrated that mice deficient in myeloid Kdm2a are protected from HFD-induced obesity, insulin resistance, and hepatic steatosis." (PMID 33462408, 2021). "As a result, mice deficient in myeloid Kdm2a were protected from HFD-induced obesity and insulin resistance." (PMID 33462408, 2021). "Previous studies have shown that KDM2A is associated with tumorigenesis, progression, poor prognosis of various cancers (esophageal squamous cell carcinoma, lung cancer, breast cancer, etc.), and obesity 18-22." (PMID 40303308, 2025). "Notably, thermogenesis was enhanced in the mouse model of Kdm2a deficiency in macrophages, and the obesity induced by HFD was prevented by enhancing H3K36me2 at the PPAR-γ locus." (PMID 37033250, 2023). "This work provides direct evidence of the exact role of KDM2A in fat deposition and provides theoretical support for obesity therapy that targets KDM2A." (PMID 34575926, 2021). "Additionally, pursuing longer HFD experiments will determine if later stages of obesity exacerbate damage in Kdm2a liver KO mice." (PMID 37892137, 2023). "Thus, considering that liver function and obesity, diabetes, and other metabolic disorders are frequently interrelated, we aimed to assess the role of KDM2A in liver function." (PMID 37892137, 2023). "Third, it has now been recognized that M2 macrophages can be therapeutically exploited to treat obesity, but additional studies would be necessary to translate our current discoveries into clinical settings, particularly for the development of Kdm2a inhibitors with minimal side effect." (PMID 33462408, 2021). "Collectively, our findings demonstrate the importance of Kdm2a-mediated H3K36 demethylation in orchestrating macrophage polarization, providing novel insight that targeting Kdm2a in macrophages could be a viable therapeutic approach against obesity and insulin resistance." (PMID 33462408, 2021). "Recent studies have shown that in KDM2A knockout in macrophages, the level of H3K36me2 at the PPARγ locus is significantly enhanced, making macrophages inclined to M2 polarization, thus preventing mice from obesity and insulin resistance induced by a high-fat diet." (PMID 34575926, 2021).